MYC (MYC proto-oncogene, bHLH transcription factor)
Diseases named in the same sentence as MYC in open-access papers (continued):
Sharing a sentence is not in itself a finding about the gene and the disease.
prostate carcinoma (continued). "The oncogene MYC, with focal gains in four cell lines (leukemia HL60 and RPMI_8226, colon carcinoma SW620 and prostate carcinoma DU_145) has been reported to be amplified in prior reports." (PMID 24670534, 2014). "In this study, we tested LPL, MYC, PTEN, CEP 7, CEP 8, and CEP 10 FISH probes, based on the published roles of these genes, and on our initial FISH study on FFPE prostate cancer and BPH specimens." (PMID 24568597, 2014). "Combined with the detection of other critical genomic biomarkers for prostate cancer such as ERG, androgen receptor, and MYC, the evaluation of PTEN genomic status has proven to be invaluable for patient stratification and management." (PMID 24062990, 2013). "We characterized AR, MYC, and TMRPSS2-ERG expression in two established primary prostate cancer xenograft models: the castration-resistant LuCaP 35CR model (formerly named LuCaP 35V;) and the neuroendocrine prostate cancer model LuCaP 145.2." (PMID 24293458, 2013). "MYC overexpression is sufficient to transform benign human prostate epithelium in vitro and MYC transgenic mice develop PIN, suggesting that MYC plays a role in prostate cancer initiation." (PMID 24293458, 2013). "Our primary prostate xenograft studies therefore confirm the activity we observed for I-BET762 in prostate cancer cell lines, and highlight the potential of BET inhibitors as therapeutic agents in prostate tumors with high MYC expression." (PMID 24293458, 2013). "In these studies, we demonstrate that BET proteins regulate MYC levels in prostate cancer models and the BET inhibitor, I-BET762, potently decreases MYC expression in cell lines and a patient-derived model with high MYC expression." (PMID 24293458, 2013). "Both c-MYC and HMGA1 have also been found to be over-expressed in prostate cancers, suggesting the importance of the PIM1/c-MYC/HMGA1 signaling cascade in prostate carcinogenesis." (PMID 22912571, 2012). "First, the effect of salinomycin on the expression of key genes involved in prostate cancer, AR, ERG and MYC was studied." (PMID 22215106, 2012). "Among these six, HLF, JUN, c-MYC, EGR1, SMAD1, and HIF1A, were also identified as PTEN-controlled TFs, and four, ESR2, MYB, RELA, and USF1, as prostate cancer-related TFs." (PMID 22347425, 2012). "Deletion of IRS2 has been found to suppress prostate cancer cell growth, proliferation and invasion in PTEN+/− mice by decreasing MYC expression and DNA synthesis." (PMID 22844442, 2012). "Through examination of 194 human prostate tumors, we observed statistically significant co-occurrence of MYC amplification and PI3K-pathway alteration, raising the possibility that these two lesions cooperate in prostate cancer progression." (PMID 21394210, 2011). "The role of PI3K signaling in prostate cancer has been modeled in mice by deletion of PTEN or by transgenic expression of activated AKT, while the role of MYC has been investigated by transgenic expression of MYC." (PMID 21394210, 2011). "Due to growing interest in evaluating PI3K-pathway inhibitors in prostate cancer patients, we explored the activity of the rapamycin analog RAD001 in the MPAKT/Hi-MYC model." (PMID 21394210, 2011). "We found a significant enrichment of MYC at the promoters of CTDSPL, CTDSP2 and CTDSP1 in both prostate cancer cell lines." (PMID 21941025, 2011). "Next, we obtained mRNA from 18 matched normal and primary prostate cancer specimens and confirmed that MYC and EZH2 mRNA were indeed overexpressed in the prostate cancers (Wilcoxon signed ranked test, p<0.0002 for both)." (PMID 21941025, 2011). "In human prostate cancer, PIM1 expression is known to be elevated in ~50% of human prostate cancer specimens and its cooperation with MYC was also proposed." (PMID 20515470, 2010).
prostate carcinoma (continued). "A 5-gene recurrence predictor of prostate cancer contains KLF6, three common ARACNe-based predictions between MYC and KLF6 (FOS, JUNB and ZFP36), and PPFIA3, which is functionally related to another predicted target of KLF6 (PPFIBP2)." (PMID 18190704, 2008). "Next, breast and prostate cancer cell lines were analysed for copy numbers of the EIF3S3, MYC and TRPS1 genes." (PMID 14997205, 2004). "The TRPS1 and MYC expression levels were similar in all prostate tumour groups, whereas EIF3S3 expression was higher (P=0.029) in prostate carcinomas compared to BPH." (PMID 14997205, 2004). "In conclusion, the results indicate that overexpression of MYC and TRPS1 are rare in prostate cancer in vivo." (PMID 14997205, 2004). "However, aberrant activity of multiple other transcriptional regulators, including transcriptional cyclin-dependent kinases (CDKs), MYC and BRD4, is also critical for prostate cancer growth, metastasis and therapy resistance." (PMID 40163908, 2025). "Although no significant modulation of MYC expression was detected in our in vitro assays, MYC overexpression in clinical samples supports its established oncogenic role in prostate cancer." (PMID 41296417, 2025). "Additionally, MYC was shown to directly control EIF4EBP1 transcription in colon adenocarcinoma and prostate cancer cells, supporting that EIF4EBP1 represents a MYC target gene." (PMID 40670359, 2025). "In prostate cancer, it reduces proliferation, invasion, and migration by targeting DLX1 and IGF-1R, while sponging by oncogenic lncRNAs such as SNHG11 and MYU relieves inhibition of c-MYC, highlighting its suppressive role." (PMID 41379397, 2025). "Indeed, MYC, MCL-1, and BCL-2 are important oncoproteins in both AR-driven and AR-independent prostate cancer." (PMID 39117800, 2024). "Interestingly, CBX7 was previously reported to synergize with c-MYC to promote the growth of prostatic cancer cells or cooperate with c-MYC to produce highly aggressive B cell lymphomas, acting as an oncogene and positively correlating with c-MYC." (PMID 37791390, 2024). "Furthermore, oncogenic drivers, like the MYC gene and TMPRSS2-ERG gene’s fusions, contribute to the aggressive behavior of prostate cancer cells." (PMID 39272896, 2024). "Moreover, miR-145-5p regulates several critical oncogenes including MYC, BRAF, and NRAS, which are known promoters of prostate cancer cell proliferation and clonogenic potential when aberrantly activated." (PMID 38673886, 2024). "MYC inhibition reduced the expression of BCL-2 mRNA in PC-3 and DU145 prostate cancer cells." (PMID 38756697, 2024). "The functional link between MYC and CTCF in prostate cancer remains to be investigated." (PMID 36997534, 2023). "Furthermore, a number of mtDNA replication–related genes are upregulated in human prostate cancer, and TWNK levels correlate with MYC mRNA." (PMID 37971875, 2023). "Interestingly, CASC11 is known to enhance prostate cancer aggressiveness and is regulated by C-MYC44, while being close to the MYC gene on chromosome 8." (PMID 38057321, 2023). "In prostate cancer, overexpression of HECTD4 has been reported to result in a simultaneous decrease in both androgen receptor (AR) and MYC proteins, while knockdown of HECTD4 results in an increase in both AR and MYC proteins." (PMID 37272305, 2023).
prostate carcinoma (continued). "HNRNPH1 exhibited a clear negative correlation with MYC activation in the majority of 27 tumor types, including prostate cancer (PRAD)." (PMID 37399401, 2023). "As an example, upon comparing signaling as functions of prostate cancer development, it was clear that some gene networks are consistently similar (i.e. AR and FOXA1) whereas others are highly dependent on the ecosystem (i.e. MYC)." (PMID 37059746, 2023). "Notch signaling has been reported to become activated in prostate cancer cell lines exhibiting resistance to the clinically available AR inhibitor enzalutamide, as verified by the increased levels of cleaved NOTCH1, HES1 and c-MYC." (PMID 35954292, 2022). "Notably, AR is the target of the drug Enzalutamide, which is indicated for men with an advanced stage of the disease, or that MYC is the target of BET bromodomain inhibitors and are generally effective in castration-resistant prostate cancer cases." (PMID 35164900, 2022). "Besides, previous research has demonstrated that several transcription factors, such as FOXM1, MYC, APC/C/CDH1, and E2F, targeted RRM2 in prostate cancer." (PMID 36202136, 2022). "In addition, MYC has been identified as a target of METTL3 in acute myeloid leukemia, gastric cancer, prostate cancer, and OSCC." (PMID 36429032, 2022). "A recent study showed that MYC could be regulated by USP16, which further inhibited prostate cancer progression." (PMID 35519620, 2022). "Notably, PGC-1α inhibits c-MYC and hence ODC, which reduces polyamine production and lowers the aggressiveness and spread of prostate cancer." (PMID 36551330, 2022). "Here, we report that in prostate cancer cells, differential binding of AR and HOXB13 on account of varying MYC levels centers on genes regulated by KMT2A/MLL1, which in turn is inversely proportional to the expression of PLA2G4F in cohorts of advanced, but not localized, PCa." (PMID 36181613, 2022). "In prostate cancer, however, the expression of FBL can be upregulated by MYC." (PMID 36004921, 2022). "Notably, AR, MYC and E2F1/2 are all established Hsp90 client proteins, and targeting Hsp90 inhibits expression of AR in prostate cancer, and MYC and E2F1 in other cancers." (PMID 35406480, 2022). "In addition, previous studies have shown that DDIT4 is significantly downregulated in prostate cancer cells and that the induction of DDIT4 expression can regulate MYC, which is a downstream target of the mTOR signaling pathway." (PMID 39697534, 2021). "While the role of SPOP protein differs depending on the tumor type, in prostate cancer, SPOP seems to function as a tumor suppressor and its targets for degradation, among others, include AR, ERG, steroid receptor coactivator 3 (SRC3), BRD4, MYC, and TRIM24." (PMID 33572160, 2021). "The same study also found that GLIPR1 overexpression in prostate cancer cell lines led to a reduction in MYC expression due to GLIPR1 directly decreasing MYC transcription as well as promoting the ubiquitination and degradation of MYC protein." (PMID 31995627, 2020). "AR binding sites that are unique to CRPC were not AR-regulated in treatment-naïve prostate cancer cells or enriched in binding of common AR collaborative TFs, such as MYC." (PMID 33134178, 2020). "Furthermore, MYC overexpression has been shown to promote thioredoxin interacting protein (TXNIP) suppression in breast and prostate cancer, thus leading to increased glucose uptake to fuel glycolytic metabolism." (PMID 32932943, 2020).
prostate carcinoma (continued). "Furthermore, given that GLIPR1 was shown to down-regulate MYC in prostate cancer, the relationship between GLIPR1 expression and MYC expression in MM PCs from newly diagnosed patients was also assessed in silico." (PMID 31995627, 2020). "In tumors where MYC is not amplified, loss of the tumor suppressor adenomatous polyposis coli and activation of the WNT/β‐catenin pathway lead to transcriptional activation of MYC via TCF transcription factor, a phenomenon occasionally observed in colorectal and prostate cancers." (PMID 32310340, 2020). "Using a multicolor fluorescence in situ hybridization approach, the copy number alterations of six genes known to be involved in aggressive prostate cancer (PTEN, MYC, MEN1, PDGFB, CTTNBP2, and TBL1XR1) was explored in a group of recurrent and in a group of nonrecurrent prostate cancer patients." (PMID 31366128, 2019). "In addition, PCAT1 is a long non-coding RNA, which is known to be upregulated in prostate cancer and negatively regulates BRCA2 expression while positively affecting MYC expression." (PMID 31748536, 2019). "Although one region of the MYC promoter was bound by both ZFHX3 and ERβ, another region was only bound by ZFHX3 and not by ERβ, further indicating that ZFHX3 is a bona fide repressor of MYC transcription in prostate cancer cells." (PMID 30979864, 2019). "Provided the critical roles of MYC and TGF-β signaling in the advanced prostate cancer subtypes, our results highly suggest curcumin as a novel anti-cancer supplementary treatment option for non-indolent prostate cancer resistant to hormone and chemical therapies." (PMID 31581661, 2019). "Using 8q24 SNPs as a proxy, our results confirm an association between c-MYC and CRC risk, but do not indicate a potential modification by 25(OH)D despite a previously reported possible interaction for fatal prostate cancer risk." (PMID 31434255, 2019). "Here, the authors show that one of the canonical UPR pathways, IRE1α-XBP1 regulates c-MYC signaling to promote prostate tumorigenesis, and pharmacological inhibition of IRE1α with MKC8866 inhibits prostate cancer growth and synergizes with clinically used prostate cancer drugs." (PMID 30679434, 2019). "Using a panel of prostate cancer cell lines, we demonstrated that MYC suppression—rather than AR suppression—is a key determinant of BET bromodomain inhibitor sensitivity." (PMID 30846826, 2019). "Copy number variations in regions encompassing important prostate cancer genes, such as PTEN and CHD1 or ASAP1, MYC, and HDAC9, are predictive of cancer significance and represent useful biomarkers to distinguish low-risk prostate cancer from intermediate- and high-risk prostate cancer." (PMID 31366128, 2019). "In their first study, they investigated whether prostate cancer subtypes driven by distinct oncogenes, namely AKT1 or MYC, exhibit distinct metabolic profiles." (PMID 30791464, 2019). "Our findings indicate that being part of ERβ signaling is an important mechanism for ZFHX3’s tumor suppressor activity in prostate cancer, as ZFHX3 is clearly upregulated by activated ERβ in C4-2B cells, and repression of MYC transcription by ERβ required the interaction of ERβ with ZFHX3." (PMID 30979864, 2019). "PCA3 might be used as a biomarker for the diagnosis of prostate cancer and PCGEM1 involved in c-MYC activation and androgen receptor transcriptional activation was associated with the progression of prostate cancer." (PMID 31448238, 2019). "Importantly, TSPX also downregulates MYC expression in both LNCaP cells and TSPX-high prostate cancer specimens." (PMID 30863497, 2019).
prostate carcinoma (continued). "MYC and AKT are arguably the most prevalent driver oncogenes in prostate cancer." (PMID 29894516, 2018). "The four genes CDH1, MYC, SOS2, and CDKN1A are obtained from the prostate cancer network." (PMID 29670664, 2018). "Some c-MYC repressed genes, Bin1 and MXI1, were inactivated in advanced prostate cancer." (PMID 28264478, 2017). "In contrast, strong interactions with the MYC region were at E72U and E39–40 in LCLs but not in prostate cancer cell lines." (PMID 26979803, 2016). "To determine the mechanism by which GUTK impedes cell cycle re-entry of quiescent prostate cancer cells, we examined the protein levels of c-MYC in the presence or absence of GUTK at GI75." (PMID 27253416, 2016). "Common genes (e.g. MYC and POU5F1B) were identified in both prostate cancer cell lines." (PMID 26934861, 2016). "A number of in vitro andin vivo studies in breast and prostate cancer have demonstrated thatMYC amplification or phosphorylation lead to acquired resistance toBEZ235, and Tan andcolleagues used a PDK1 inhibitor to bypass MYC-dependent resistance." (PMID 26678268, 2015). "As SIRT3 effectively suppressed prostate cancer cell proliferation, we speculated that SIRT3 might function through the suppression of oncoprotein c-MYC." (PMID 26317998, 2015). "FOXP3 has been shown to exert its growth inhibitory effect on breast and prostate cancer cells by transcriptionally repressing the expression of specific oncogenes (HER2, SKP2, SATB1 and MYC), and inducing the expression of specific tumor suppressor genes (CDKN1A, LATS2)." (PMID 24406338, 2014). "To gain a better understanding of the mechanisms through which BET inhibitors regulate cell growth and death in prostate cancer cell lines, we analyzed basal expression of BET proteins and several oncogenes that are known drivers in prostate cancer, including ERG, MYC, and AR." (PMID 24293458, 2013). "High expression of ATAD2 has previously been found to be associated with an unfavorable prognosis in breast, lung, and prostate cancers and it has been suggested that ATAD2 contributes to the development of aggressive cancer through linking of the E2F and MYC pathways." (PMID 23393560, 2013). "In DU145 and PC3 cells that had been depleted of MYC by siRNA-mediated knockdown, we observed reduced EZH2 promoter activity (p<0.02 for both cell lines),indicating that MYC can indeed activate EZH2 transcription in prostate cancer cell lines." (PMID 21941025, 2011). "MYC and phosphoinositide 3-kinase (PI3K)-pathway deregulation are common in human prostate cancer." (PMID 21394210, 2011). "A potential cooperative role for PI3K-pathway activation and the MYC oncogene has not yet been documented in human prostate cancer, although pathway-interaction has been suggested by several in vitro and in vivo models." (PMID 21394210, 2011). "In order to evaluate the significance of EIF3S3, MYC, and TRPS1 in breast and prostate cancer, we have analysed the expression and copy number of the three genes in cell lines and tumours using quantitative real-time RT–PCR and fluorescence in situ hybridisation (FISH)." (PMID 14997205, 2004). "Furthermore, gene set enrichment analysis unveiled differential enrichment of pathways such as myogenesis, interferon γ and α responses, and the MYC proto-oncogene pathway in tumors with elevated GABRB3 expression, implying a role for GABRB3 in prostate cancer." (PMID 38287309, 2024). "In addition, it was shown that M4N suppressed the expression of MYC mRNA in LNCaP prostate cancer cells and AsPC1 pancreatic cancer cells but not in L428 leukemic cells when they were treated with M4N for several hours." (PMID 39590335, 2024). "In addition to over-riding programmed cell death responses via upregulation of anti-apoptotic factors, CDK9 also promotes the expression and/or activity of oncogenic transcription factors such as MYC, NF-κB, BRD4, and STAT3, all of which are established drivers of prostate cancer progression." (PMID 39117800, 2024).